LEPR (leptin receptor)
Diseases named in the same sentence as LEPR in open-access papers (continued):
Sharing a sentence is not in itself a finding about the gene and the disease.
Sepsis (7 papers, 2010 to 2025). Sepsis is defined as life-threatening organ dysfunction caused by a dysregulated host response to infection. "In agreement with the evidence that shows the beneficial actions of leptin during sepsis and endotoxemia, the alteration of the leptin receptor has been associated with higher mortality in patients with peritonitis." (PMID 30618812, 2018). "As far as we know, this is the first report of the association between LEP and LEPR genetic polymorphisms and death, in any form of sepsis." (PMID 21943151, 2011). "Evidence that mortality is variably increased or decreased in leptin receptor-deficient db/db mice subject to CLP-modelled sepsis adds to the uncertainty on whether leptin is a follower or driver of sepsis progression, and further research is required to confirm the nature of this interaction." (PMID 39968295, 2025). "In line with previous reports, we observed that sepsis boosted SNS activity to reduce medullar SCF levels by acting on β3-adrenergic receptors present on the LepR+ perivascular cells and, in turn, allowing the release of MEPs into the circulation." (PMID 35192546, 2022). "In mouse endotoxemia and cecal ligation puncture models of sepsis, elevated levels of leptin and soluble leptin receptor have been observed." (PMID 31877773, 2019). "The exact functional contribution of soluble leptin-receptor or free leptin in the pathogenesis of critical illness or sepsis is currently unclear, and additional studies in experimental models are warranted." (PMID 20871818, 2010). "In sepsis, endothelial cells expressed lower Cxcl12 mRNA, and LepR+ cells expressed lower Scf mRNA." (PMID 35192546, 2022). "Upon admission to Medical Intensive Care Unit (ICU), free leptin and soluble leptin-receptor serum concentrations were determined in 137 critically ill patients (95 with sepsis, 42 without sepsis) and 26 healthy controls." (PMID 20871818, 2010). "Although leptin and leptin-receptor serum concentrations do not differ in patients with critical illness or in the subgroups of patients with and without sepsis from healthy controls, serum leptin in critically ill patients is closely correlated with the patients' BMI and metabolic alterations." (PMID 20871818, 2010).
thyroid cancer (7 papers, 2015 to 2021). "Studies of thyroid cancer have also shown that downregulation of LEPR was associated with increased risk of thyroid cancer recurrence and metastasis, particularly in the anaplastic thyroid cancer (ATC) subtype." (PMID 32046756, 2020). "Meanwhile, leptin receptor exists in all thyroid cancer cells." (PMID 32819324, 2020). "Leptin acting via leptin receptor may regulate cell migration of thyroid cancer cells." (PMID 27050378, 2016).
Abdominal obesity (6 papers, 2013 to 2022). Excessive fat around the stomach and abdomen. "It is reported that ablation of LEPR causes severe growth hormone deficiency and abdominal obesity in male mice." (PMID 29301582, 2018). "Disagreement with these findings, gains in copy numbers of LEPR and neuronal growth regulator 1 (NEGR1) gene were associated with a decreased body mass index, waist circumference and risk of abdominal obesity in human." (PMID 30134528, 2018). "Increased central obesity normally leads to increased leptin that could be responsible for the decrease in testosterone level previously reported among this population via functional leptin receptor isoform on Leydig cells." (PMID 23895401, 2013).
cognitive decline (6 papers, 2016 to 2023). "In this study, Zucker diabetic fatty (ZDF) rat harboring a missense mutation (fatty, fa) in the leptin receptor gene (LEPR) was used to determine whether ZBPYR improves cognitive decline by regulating gut microbiota." (PMID 28099913, 2017). "This study explored the relationship between retinal thinning and cognitive decline in the LepR db/db model of T2D." (PMID 37850093, 2023). "Leptin receptor-deficient mice, a T2DM model, had an age-dependent cognitive decline with reduced synaptic density and increased tau phosphorylation." (PMID 27884163, 2016). "The results indicated that mild CCH decline could not induce a cognitive decline in the LepR-deficient db/db mice as it did in the wild-type mice, and LepR deficiency might protect the db/db mice from the severe damage that CCH would have caused." (PMID 33380900, 2020).
diabetic nephropathy (6 papers, 2013 to 2025). "Conversely, adoptive transfer of Tregs into leptin receptor null mice improved their insulin sensitivity and diabetic nephropathy." (PMID 23936084, 2013). "Ginsenosides have been evaluated in diverse animal models of diabetic kidney disease, including high-fat diet (HFD) and streptozotocin (STZ)-induced rodent models and Db/Db mice with leptin receptor mutations, to assess their protective effects against diabetic kidney disease." (PMID 41415561, 2025). "Treg depleted mice had more severe diabetic nephropathy, and increased inflammatory cells in their visceral adipose tissue and kidneys compared to leptin receptor deficient mice that were not depleted of Tregs." (PMID 23936084, 2013).
endothelial dysfunction (6 papers, 2015 to 2023). In vascular diseases, endothelial dysfunction is a systemic pathological state of the endothelium (the inner lining of blood vessels) and can be broadly defined as an imbalance between vasodilating and vasoconstricting substances produced by (or acting on) the endothelium. "Previous experimentation on murine and canine models suggests that coronary arteries with the leptin receptor were associated with increased endothelial dysfunction in the presence of obese-level concentrations of leptin, but normal endothelial function in normal levels of leptin." (PMID 31466225, 2019). "Increased leptin hormone and leptin receptor may enhance the generation of proinflammatory cytokines by endothelial cells and lead to endothelial dysfunction." (PMID 29379664, 2017).
leukemia (6 papers, 2016 to 2026). A malignant (clonal) hematologic disorder, involving hematopoietic stem cells and characterized by the presence of primitive or atypical myeloid or lymphoid cells in the bone marrow and the blood. "Deletions of 6q involving FOXO3 and/or PRDM1 may therefore promote leukaemia survival partly by reducing sensitivity to leptin receptor signalling." (PMID 36670235, 2023). "In mouse models, fasting induced leptin receptor activity was shown to promote B- and T-ALL differentiation and reduce leukaemia burden in a manner dependent on induction of PRDM1." (PMID 36670235, 2023). "Loss of normal hematopoiesis is a classical event during human myeloproliferative neoplasias and leukemias where the niche downregulate essential HSPC retention factors as CXCL12, SCF, LepR, Angpt1, Cdh2, Slit2, and TGF-β1 though pro-inflammatory factors secreted by leukemia-initiating cells." (PMID 28111575, 2016).
meningioma (6 papers, 2016 to 2023). A generally slow growing tumor attached to the dura mater. "Gene expression signature shows its association of patient survivals and another panel of two gene (PTTG1 and LEPR) expressions demonstrates association with the recurrent meningioma." (PMID 33807688, 2021). "Although the biological regulation of LEPR in meningioma is still unclear, a few observative studies uncover patients with meningioma are prone to be obese." (PMID 33807688, 2021). "In our MPscore gene reference, LEPR is another well-characterized prognostic biomarker and independent predictive biomarker for meningioma." (PMID 33807688, 2021). "Although found to be overexpressed in some cancers, LEPR expression was downregulated in high grade meningioma in this study as well as in two previous meningioma studies." (PMID 33167358, 2020). "However, as a prognostic biomarker of disease aggressiveness, LEPR has also shown promise in several other cancers including prostate, endometrial and thyroid, indicating that its value in meningioma prognosis ought to be investigated further." (PMID 33167358, 2020). "Moreover, multivariate survival analysis established increased PTTG1 and decreased LEPR expression as novel and potentially powerful prognostic markers for the identification of clinically aggressive meningiomas." (PMID 26894859, 2016). "However, molecular mechanisms of LEPR regulation and its influence on intracellular signaling in meningiomas are still unknown." (PMID 26894859, 2016). "Among these, PTTG1 and LEPR showed a significant association with recurrence independent of known prognostic confounders such as WHO grade and therefore might serve in the future as novel putative biomarkers to predict aggressiveness of meningiomas." (PMID 26894859, 2016). "In accordance with our findings, the remaining four top genes were previously found to be either upregulated (UBE2C and PRC1) or downregulated (LEPR and MN1) in WHO grade II and III meningiomas." (PMID 26894859, 2016). "In WHO°II meningiomas reduced expression of LEPR and MN1 resulted in a significantly shorter PFS, while in WHO°III meningiomas this was the case for a higher expression levels of PTTG1 and UBE2C." (PMID 26894859, 2016).
neuroblastoma (6 papers, 2014 to 2022). Neuroblastoma (NB) is the most common solid, extracranial childhood tumor. "The present study examined the effect of homocysteine on leptin signaling in SH-SY5Y neuroblastoma cells expressing the leptin receptor Ob-Rb." (PMID 36512575, 2022). "To test leptin’s effect on Hsp10 expression in vitro, we used the transgenic cell line SH-SY5Y (neuroblastoma cells) overexpressing the long isoform of leptin receptor (ObRb)." (PMID 33946318, 2021). "A human neuroblastoma cell line stably transfected with the Ob-Rb leptin receptor (SH-SY5Y-ObRb) was treated with insulin (300 nM, 4 h)." (PMID 27677243, 2016). "Leptin (0.5 μg/mL, 15 min) was administered to a SH-SY5Y human neuroblastoma cell line stably transfected with Ob-Rb leptin receptor (SH-SY5Y Ob-Rb), and the cells were analyzed for STAT3 and STAT5 activation." (PMID 27746736, 2016). "SH-SY5Y, a human neuroblastoma cell line stably transfected with the Ob-Rb leptin receptor (SH-SY5Y-ObRb), was treated with leptin." (PMID 25403445, 2014).
systemic lupus erythematosus (6 papers, 2012 to 2023). An autoimmune multi-organ disease typically associated with vasculopathy and autoantibody production. "LEPR rs1892535 and rs6690625 were associated with a diminished risk of lupus in a population Hispanic enriched for the Amerindian European admixture." (PMID 35967162, 2022). "Leptin receptor deficiency blocks the inhibitory effect of leptin on SLE Tfh cell differentiation, serving as a promising therapeutic target for lupus management." (PMID 37006245, 2023). "To test the translational application of LepR-based therapeutic strategy for SLE treatment, we established humanized lupus chimeras in which immune-deficient NSG mice were reconstituted with PBMCs from active lupus patients." (PMID 37006245, 2023). "Using the humanized lupus model, we tested whether targeting LepR by genetic overexpression could protect the chimeras from Tfh cell mal-differentiation and IgG anti-dsDNA generation." (PMID 37006245, 2023). "The keywords used included leptin, leptin receptor, level, systemic lupus erythematosus, and SLE." (PMID 35967162, 2022). "Accordingly, overexpression of leptin receptor in SLE CD4 T cells abrogated Tfh cell mal-differentiation and IgG anti-dsDNA generation in humanized lupus chimeras." (PMID 37006245, 2023). "Of importance, LepR is therapeutically targetable as overexpression of LepR rescues the inhibitory effect of leptin on SLE Tfh cell differentiation, and blocks IgG autoantibody production in humanized lupus chimeras." (PMID 37006245, 2023).
cardiomyopathy (5 papers, 2018 to 2024). A disease of the heart muscle or myocardium proper. "Next, we explored whether decreased BCAA levels increase the risk of cardiomyopathy in both an STZ/HFD-induced T2D mouse model (STZ/HFD T2D mice) and a leptin receptor-deficient (db/db) mouse model of induced T2D." (PMID 39659577, 2024).
coronary artery disease (5 papers, 2014 to 2025). "Genetic evidence from different human populations has implicatedLEP/LEPR in the pathogenesis of coronary artery disease (CAD), and suggeststhat certain LEP/LEPR gene polymorphisms may increase the risk of CAD." (PMID 32049202, 2020).
diabetic cardiomyopathy (5 papers, 2014 to 2025). Diabetic cardiomyopathy is a disorder of the heart muscle in people with diabetes. "However, in a diabetic cardiomyopathy model using leptin receptor-deficient db/db mice, cMyBP-C phosphorylation levels were significantly elevated, similar to what we observed in our study." (PMID 39485297, 2024).
endometriosis (5 papers, 2013 to 2025). The growth of functional endometrial tissue in anatomic sites outside the uterine body. "There is a significant association of the LEPR rs1137100 polymorphism with chronic pelvic pain (OR=1.75; CI 95%=1.05-2.89) and dyspareunia (OR=1.78; CI 95%=1.01-3.12) in women with endometriosis." (PMID 40673025, 2025). "The present study provides a clue for future investigations to understand the contribution of genetic polymorphisms of the leptin receptor in the genetic predisposition to endometriosis-related symptoms." (PMID 40673025, 2025). "In the same study, the leptin receptor-deficient mouse also demonstrated similar impairments in endometriosis development as those treated with pegylated leptin peptide receptor antagonists." (PMID 36140261, 2022). "In conclusion, the LEPR rs1137100 SNP may be associated with greater susceptibility to chronic pelvic pain and dyspareunia in women with endometriosis." (PMID 40673025, 2025). "Therefore, this study aims to evaluate the role of the LEP rs7799039 and LEPR rs1137100 polymorphisms in the painful symptoms of endometriosis in Brazilian women." (PMID 40673025, 2025). "Our findings suggest that the LEPR rs1137100 polymorphism is associated with increased endometriosis-related gynecological pain and may be a potential target for molecular diagnosis of the disease and development of individualized treatment strategies." (PMID 40673025, 2025). "Therefore, in the present study, the association of the LEPR rs1137100 A>G SNPs with the prevalence of painful symptoms of 237 women with endometriosis in the Brazilian population was explored." (PMID 40673025, 2025). "However, obese recipient mice with leptin deficiency and leptin receptor deficiency showed suppressed endometriosis development compared with control mice." (PMID 36140261, 2022). "Furthermore, donor uterine tissues with leptin deficiency and leptin receptor deficiency suppressed endometriosis development compared with control donor in control recipient mice." (PMID 36140261, 2022). "Endometriosis pain is associated with inflammatory cytokines, such as leptin (LEP), through activation with its receptor (LEPR), and its expression can be influenced by the presence of genetic polymorphisms." (PMID 40673025, 2025). "In this study, leptin/BMI ratio in serum and peritoneal fluid and gene expression of leptin and long form leptin receptor (OB-RL) were assessed in eutopic and ectopic endometria of women with endometriosis and controls." (PMID 23634146, 2013). "The paper entitled “Gene expression of leptin and long leptin receptor isoform in endometriosis: a case-control study” is an original clinical study suggesting a putative role of leptin in the development of endometrial implants." (PMID 24379834, 2013). "Interestingly, only a few studies so far have evaluated leptin receptor gene and/or protein expression in endometrial tissue of women with endometriosis." (PMID 23634146, 2013). "The increase in leptin and leptin receptor expression in the ectopic endometrium of women with endometriosis may lead to increased leptin signaling in implants, resulting in proliferation, neoangiogenesis, and maintenance of ectopic endometrial tissue." (PMID 23634146, 2013). "In a mouse model of endometriosis, HFD-induced obese mice increased lesion number and weight, which depended on leptin or leptin receptor." (PMID 38559689, 2024). "Another limitation, leptin levels and LEPR expression in women with endometriosis and in different genotypes could not be directly determined due to the lack of an adequate sample for measurement." (PMID 40673025, 2025).
malnutrition (5 papers, 2013 to 2025). Inadequate nutrition resulting from poor diet, malabsorption, or abnormal nutrient distribution. "Mice lacking the leptin receptor are highly susceptible to infection from protozoa, pneumonia and Listeria demonstrating how malnutrition can compromise Th1 driven immunity." (PMID 23349631, 2013).
myocardial infarction (5 papers, 2011 to 2025). Gross necrosis of the myocardium, as a result of interruption of the blood supply to the area, as in coronary thrombosis. "Roszkowska-Gancarz9 reported that polymorphisms at LEP rs7799039 and LEPR rs1137100 wereassociated with risk of myocardial infarction, a type of CAD, in a Polishpopulation." (PMID 32049202, 2020). "Roszkowska-Gancarz M.’s9 study showed that the LEPR rs1137100 polymorphism significantly differsbetween centenarians and myocardial infarction groups." (PMID 32049202, 2020). "Moreover, chronic leptin infusion increased cardiac ANP expression after myocardial infarction (MI) in mice, whereas neutralizing LepR antibodies abrogated the hypertrophy of the surviving myocardium after coronary artery ligation in rats." (PMID 23841921, 2013). "Studies from our laboratory showed that CNS LepR activation, without raising plasma leptin levels, has remarkable beneficial effects on cardiac metabolism and function that protect the heart during pathological conditions, including heart failure (HF) induced by myocardial infarction (MI)." (PMID 39612121, 2024).
renal cell carcinoma (5 papers, 2011 to 2025). "Background and Objectives: To investigate the clinical significance of adipokines’ [leptin, leptin receptor (leptin-R), adiponectin, and resistin] expression on the characteristics and survival outcomes of patients with renal cell carcinoma (RCC)." (PMID 41010935, 2025). "In untreated and newly diagnosed patients with renal cell carcinoma, promoter methylation in the leptin gene (LEP), as well as leptin receptor gene (LEPR), is remarkably higher in tumor tissues compared with normal adjacent tissues." (PMID 38405061, 2024).
Stroke (5 papers, 2014 to 2025). Sudden impairment of blood flow to a part of the brain due to occlusion or rupture of an artery to the brain. "Although stroke is an important issue and the existing evidence suggests that the association between the LEPR gene variant and stroke may exist, very few studies have evaluated its relationship." (PMID 28368354, 2017). "Firstly, leptin induces neurogenesis and angiogenesis after stroke and leads to increased leptin receptor and pAMPK concentrations." (PMID 25061971, 2014). "Moreover, there is a correlation between genetic variations in the leptin receptor (LEPR) gene and a higher susceptibility to stroke and other cardiovascular issues." (PMID 39931847, 2025).